POU3F2 (POU class 3 homeobox 2)
Description:
Transcription factor that plays a key role in neuronal differentiation (By similarity). Binds preferentially to the recognition sequence which consists of two distinct half-sites, ('GCAT') and ('TAAT'), separated by a non-conserved spacer region of 0, 2, or 3 nucleotides (By similarity). Acts as a transcriptional activator when binding cooperatively with SOX4, SOX11, or SOX12 to gene promoters (By similarity). The combination of three transcription factors, ASCL1, POU3F2/BRN2 and MYT1L, is sufficient to reprogram fibroblasts and other somatic cells into induced neuronal (iN) cells in vitro (By similarity). Acts downstream of ASCL1, accessing chromatin that has been opened by ASCL1, and promotes transcription of neuronal genes (By similarity).
Synonyms: Brn-2; Oct-7; OTF-7; BRN2; OCT7; OTF7; POUF3; N-Oct3
Tractability: PROTAC: ubiquitination databases record sites on it.
Target class: Transcription factor
Gene: Protein-coding gene on chromosome 6 (98,834,574 to 98,839,458, forward strand). Ensembl gene ENSG00000184486.
Subcellular location: Nucleus
Subcellular location (Human Protein Atlas): Nucleoplasm
Pathways (Reactome):
Developmental Biology: EGR2 and SOX10-mediated initiation of Schwann cell myelination; Regulation of MITF-M-dependent genes involved in apoptosis; Transcriptional and post-translational regulation of MITF-M expression and activity
Gene Ontology:
Molecular function: identical protein binding; protein binding; sequence-specific double-stranded DNA binding; DNA binding; DNA-binding transcription factor activity; DNA-binding transcription factor activity, RNA polymerase II-specific; RNA polymerase II cis-regulatory region sequence-specific DNA binding; DNA-binding transcription activator activity, RNA polymerase II-specific; sequence-specific DNA binding
Biological process: positive regulation of cell population proliferation; nervous system development; neuron development; neuron differentiation; neuron fate commitment; neuron fate specification; positive regulation of transcription by RNA polymerase II; regulation of transcription by RNA polymerase II; brain development; negative regulation of gene expression; regulation of DNA-templated transcription
Cellular component: nucleoplasm; chromatin; RNA polymerase II transcription regulator complex; nucleus; transcription regulator complex
Genetic constraint (gnomAD): Loss-of-function variants: 11 observed, 22.14 expected, observed/expected ratio (o/e) 0.5, 90% interval 0.31 to 0.82. The synonymous counts are far from expectation, so gnomAD's model fits this gene poorly and the ratio says little. Missense variants: 419 observed, 513.15 expected, observed/expected ratio (o/e) 0.82, 90% interval 0.75 to 0.88. Synonymous variants: 296 observed, 232.63 expected, observed/expected ratio (o/e) 1.27, 90% interval 1.16 to 1.4.
Homologues: Orthologues: dog POU3F2 (100% identical), mouse Pou3f2 (100% identical), macaque POU3F2 (99% identical), rat Pou3f2 (99% identical), pig POU3F2 (99% identical), tropical clawed frog pou3f2 (72% identical), zebrafish pou3f2b (67% identical), guinea pig POU3F2 (58% identical), Drosophila melanogaster acj6 (23% identical), Caenorhabditis elegans unc-86 (21% identical). Paralogues in human: POU3F3 (63% identical), POU3F4 (53% identical), POU3F1 (49% identical), POU2F1 (31% identical), POU2F2 (30% identical), POU2F3 (29% identical), POU5F1 (27% identical), POU5F1B (27% identical), POU4F2 (24% identical), POU4F3 (24% identical), POU1F1 (24% identical), POU6F2 (24% identical), and 5 more.
Diseases named in the same sentence as POU3F2 in open-access papers:
POU3F2 is named in the same sentence as 70 diseases in open-access papers, as found by Europe PMC text mining. Sharing a sentence is not in itself a finding about the gene and the disease. The quoted sentences say what the papers report.
melanoma (86 papers, 2006 to 2026). A malignant, usually aggressive tumor composed of atypical, neoplastic melanocytes. "Changing of expression of the Microphthalmia-associated Transcription Factor (MITF) and the POU domain transcription factor BRN2 (POU3F2) have already been linked to the metastatic mechanism of phenotype switching in malignant melanoma." (PMID 38773108, 2024). "Upregulation of POU3F2 represses Microphthalmia-associated transcription factor (MITF) expression in some melanomas by binding to its promoter region, which drives the cells to adopt a more stem-like and aggressive phenotype." (PMID 35546872, 2022). "A member of the POU domain family of transcription factors, BRN2 (encoded by the gene POU3F2), is thought to play important roles in melanoma formation, progression as well as metastasis." (PMID 32632141, 2020). "Collectively, these results indicated that LINC00662 acted as a ceRNA to regulate POU3F2 expression by sponging miR-107 in melanomas." (PMID 38169586, 2024). "Overall, our results confirmed that LINC00662 promoted melanoma progression by sponging miR107 and inducing POU3F2, highlighting the mechanism of the LINC00662/miR-107/POU3F2 axis in melanoma cell proliferation and invasion." (PMID 38169586, 2024). "Overall, these results confirmed that POU3F2 was a downstream target of LINC00662/miR107, and that LINC00662 participated in the development of melanomas by binding miR-107 and activating POU3F2." (PMID 38169586, 2024). "BRN2, the POU domain transcription factor encoded by the gene POU3F2, has been linked to melanoma progression in the phenotype switching model as a potential driver of invasive behaviour [reviewed in]." (PMID 37181747, 2023). "In melanoma, miR-107 functions as a tumor suppressor by binding in the 3’UTR of POU3F2, a transcription factor regulating melanoma cell invasiveness and proliferation." (PMID 36612285, 2022). "BRN2 (Brain-Specific Homeobox/POU Domain Protein class 3 transcription Factor 2 or POU3F2), a transcription factor, is associated with aggressive melanoma development, and MIR211 is a strong suppressor of BRN2 mediated invasiveness." (PMID 33628737, 2020). "Together with the past studies, our work confirms the important function of POU3F2 in driving melanoma tumorigenesis and its metastatic transformation." (PMID 32169117, 2020). "POU3F2 protein expression was significantly upregulated in both primary melanoma and metastatic tumors." (PMID 32169117, 2020). "Based on miRNA target prediction, a conserved binding site was found in the 3′UTR of POU3F2, a transcription factor found regulating invasiveness and proliferation of melanoma cells in a recent study." (PMID 32169117, 2020). "Inhibiting miR-211 leads to the increased POU3F2 and subsequently promotes invasive potential of melanoma cells." (PMID 32169117, 2020). "To produce the clinical insight of POU3F2 in melanoma, we moved on to compare its expression among three clinical sample groups: nevi from non-tumor tissues, primary melanoma and metastatic melanoma." (PMID 32169117, 2020). "In the open wound closure assay, transfection of POU3F2 was shown to abolish the inhibitory effect of miR-107 on melanoma cell migration rate." (PMID 32169117, 2020). "A subsequent study has proposed both MITF and POU3F2 are critical for metastatic growth of melanoma in vivo." (PMID 32169117, 2020). "Taken together, these tests indicated POU3F2 was a functional downstream target of miR-107 in melanoma." (PMID 32169117, 2020). "Heterogeneous expression of the Microphthalmia-associated Transcription Factor (MITF) and the POU domain transcription factor BRN2 (POU3F2) has been found in malignant melanoma." (PMID 28883623, 2017). "The PI3K pathway mediates angiogenesis and the expression of growth factors in endothelial cells and also regulates Pou3f2 in melanoma cells." (PMID 28323620, 2017).
melanoma (continued). "It has been well documented that miR-211 is a lineage-specific miRNA which is highly expressed in the melanocytic lineage and has been associated with melanoma cell invasiveness via its direct regulation of POU3F2 (BRN2), IGF2R, TGFBR2, NFAT5, and NUAK1." (PMID 25980496, 2015). "In addition, correlation analysis revealed that POU3F2 positively correlates with the expression of LINC00662 in melanoma." (PMID 38169586, 2024). "We hypothesized that LINC0062 might be involved in the development of melanoma via regulating the miR107/POU3F2 axis." (PMID 38169586, 2024). "To further confirm this hypothesis, we measured the expression level of POU3F2 in melanoma cells by RT-qPCR." (PMID 38169586, 2024). "Notably, our study identified POU3F2 as a downstream gene of the LINC00662/miR-107 axis in melanoma." (PMID 38169586, 2024). "We aimed to demonstrate that LINC00662 may regulate POU3F2 expression in melanoma by competitively binding miR-107 in this study." (PMID 38169586, 2024). "Our findings suggested that the LINC00662/miR-107/ POU3F2 axis may be one of the ways that LINC00662 promotes melanoma growth and metastasis." (PMID 38169586, 2024). "In a previous report, miR-107 acted as a tumor suppressor by targeting POU3F2 19, thus, we hypothesized that POU3F2 was involved in the LINC00662/miR-107-dependent pathway in melanoma." (PMID 38169586, 2024). "PI3K signalling is reported to act upstream of POU3F2 in melanoma." (PMID 32169117, 2020). "Similarly, brain-specific homeobox/POU domain protein 2 (BRN2), also known as POU3F2, has been shown to promote melanoma metastasis." (PMID 33024276, 2020). "Over-expressing POU3F2 reverses the inhibitory effect of miR-107 on melanoma cells." (PMID 32169117, 2020). "Interestingly, the POU3F2 expression pattern in melanoma tissues was inversely correlated with miR-107." (PMID 32169117, 2020). "In melanoma, POU3F2 has been proposed as a key driver for tumour progression and metastasis." (PMID 32169117, 2020). "Last but least, we addressed whether POU3F2 was required for miR-107-mediated suppression of melanoma cells." (PMID 32169117, 2020). "Over-expression of POU3F2 antagonized miR-107-mediated inhibitory effect on melanoma cells." (PMID 32169117, 2020). "Among the genes considered putatively involved in chromatin remodeling, two were present as down-expressed among our DEGs, POU3F2 (transcription factor, logFC = –1.549) classified as a melanoma gene, and IRF4 (interferon, logFC = -1.833) classified as a skin neoplasma gene." (PMID 30485296, 2018). "In human melanoma spheres and tumor xenograft, Pou3f2 is proposed to induce the Notch pathway." (PMID 28323620, 2017). "For example, oncogenic BRAF has been shown to support the proliferation and survival of melanoma cells through the upregulation of POU3F2 and MITF, and POU3F2 expression appears to be important for the proneural/neuroendocrine differentiation of lung cancer cells." (PMID 27271588, 2016). "In addition, reduced MITF expression levels would occur when POU3F2 expression is elevated, and this would also correspond to instances in vivo in melanoma tissues when pigment production is reduced." (PMID 24062982, 2013). "High expression of POU3F2 in melanoma represseses MITF expression." (PMID 24062982, 2013). "Indeed, POU3F2 is part of the phosphatidylinositol 3-kinase (PI3K)-PAX3-POU3F2 (BRN2) axis that has been proposed to promote melanoma cell invasion." (PMID 24062982, 2013). "Thus, our study suggested that the LINC00662/miR-107/POU3F2 axis may play an important role in melanoma progression." (PMID 38169586, 2024).
melanoma (continued). "Notably, a previous study has shown that miR-107 was a novel tumor suppressor targeting POU3F2 in melanoma 19, and our bioinformatics analysis predicted that miR-107 could be a target of LINC00662." (PMID 38169586, 2024). "In the broader CCLE melanoma cell lines dataset, the overall expressions of TRPV2 and POU3F2(BRN2) were also correlated." (PMID 36744297, 2023). "We, therefore, investigated TRPV2 expression with respect to melanoma invasiveness, by quantifying TRPV2 transcripts along with POU3F2(BRN2) transcription factor mRNAs, a well‐established marker of the melanoma invasive phenotype." (PMID 36744297, 2023). "On the other hand, miR-211 can block the invasion and migration of melanoma cells, and repress POU3F2 (POU-domain class 3 transcription factor 2, also known as brain-specific homeobox 2 (BRN2)) which acts as a MITF suppressor." (PMID 36224606, 2022). "In addition, it may alter the motif of POU3F2, a transcription factor (TF) present in melanoma cell lines known to alter the expression of pigmentation genes (i.e. MITF, KITLG), although a recent study suggests that this TF does not have a role in normal skin melanocytes." (PMID 35712076, 2022). "In these cells, we identified several known melanoma PAX3 targets, including MITF and BRN2/POU3F2." (PMID 40428399, 2025). "The overexpression of POU domain, class 3, transcription factor 2 (POU3F2), a downstream target of miR-107, antagonized miR-107-mediated suppression of melanoma cells, highlighting miR-107 as a novel tumor suppressor during melanoma metastasis." (PMID 40861221, 2025). "The negative effect of silencing LINC00662 on melanoma cell proliferation and migration was partially abrogated by miR-107 mimetic inhibitors or POU3F2 overexpression." (PMID 38169586, 2024). "Our results revealed that the simultaneous existence of YB-1 and the other four (SOX2, POU3F2, OCT-4, and OLIG1) or five (SOX2, SALL2, OCT-4, POU3F2, and Bmi-1) transcription factors reverted YB-1-deleted melanoma stem cells or breast cancer stem cells, respectively, into cancer stem cells." (PMID 31375149, 2019). "PAX3 is activated by PI3 K (phosphatidylinositol 3-kinase) and STAT3 (signal transducer and activator of transcription 3) in melanoma cells, and a negative PAX3-dependent regulation of MITF expression is mediated by BRN2 encoded by POU3F2." (PMID 25433395, 2015). "Interestingly, in two other “lower MITF” expressing melanoma cell lines (i.e., NZM9 and NZM40) there were undetectable levels of POU3F2 expression." (PMID 24062982, 2013). "It is possible that these “lower MITF” melanoma cell lines have an alternative pathway to suppress MITF that does not involve POU3F2 expression." (PMID 24062982, 2013). "In addition to competitively targeting the expression of miR-107 and then regulating the downstream gene POU3F2, whether LINC00662 has another mechanism of action in melanoma to regulate tumor progression requires further verification." (PMID 38169586, 2024). "Due to the phenotype switching model in melanoma as one main model for heterogeneity and plasticity, we screened the EnrichR analysis for the enrichment of relevant transcription factor target genes in the CHEA database, namely genes with MITF and POU3F2 (Brn2) binding site, respectively." (PMID 34439267, 2021). "Also, miR-211 revealed an important role in the regulation of POU3F2, the POU domain transcription factor that is better known as BRN2, a well-established MITF repressor, suggesting a further indirect influence of miR-211 in the development of melanoma metastasis." (PMID 32013263, 2020). "We chose to focus on miR-107 because of the specificity of miR-107 expression in melanomas, as well as the lack of related studies, and because LINC00662 was positively correlated with the expression of POU3F2, a downstream target of miR-107." (PMID 38169586, 2024).
glioblastoma (29 papers, 2015 to 2025). The most malignant astrocytic tumor (WHO grade IV). "In glioblastoma stem cells (GSCs), for example, the expression levels of key stemness-related TFs (POU3F2, SOX2, SALL2, and OLIG2) are significantly higher than those in more differentiated tumor cells." (PMID 37370081, 2023). "A recent study identified four transcription factors (SOX2, SALL2, OLIG2, and POU3F2) as the minimal core sufficient to reprogram differentiated glioblastoma (GBM) cells into stem-like cells." (PMID 34282187, 2021). "A more recent study has shown that the tumor-propagating potential of glioblastoma cells can be enhanced by increasing the expression of a set of transcription factors normally involved in neuronal development, including POU3F2, SOX2, SALL2 and OLIG2." (PMID 29609590, 2018). "We found that ARNT2 knockdown decreased the expression of SOX9, POU3F2 and OLIG2, transcription factors implicated in glioblastoma cell tumorigenicity, and repressed glioblastoma stem-like cell tumorigenic properties in vivo." (PMID 29149419, 2018). "We herein found that expression of SOX2 was decreased, whereas expression of OLIG2 and POU3F2 were increased in both rat and human glioblastoma cell lines under sphere culture conditions." (PMID 28717188, 2017). "Here SWIM implicated FOSL1 as a putative master regulator of a core of four master neurodevelopmental transcription factors (i.e., SOX2, SALL2, OLIG2, POU3F2), whose induction was demonstrated to be sufficient to reprogram fully differentiated glioblastoma cells into stem-like cells." (PMID 33785068, 2021). "Moreover, its expression is a recognized marker of the proneural subtype of glioblastomas and, even more importantly, in cooperation with Sox2, Pou3f2 and Sall2, Olig2 is a key master transcription factor of glioblastoma-initiating cells." (PMID 32316617, 2020). "In neurosphere assays of human glioblastoma cell lines, silencing METTL3 reduces the expression of glioblastoma reprogramming factors POU3F2, SOX2, SALL2, and OLIG2, and inhibits glioblastoma cell proliferation." (PMID 39473440, 2024). "In line with its neural and stem cell renewal function, SALL2, combined with SOX2, POU3F2, and OLIG2 transcription factors, promotes the de-differentiation of glioblastoma cells into stem-like tumor propagating cells." (PMID 33692826, 2021). "In glioblastoma multiforme (GBM), a core set of neuro-developmental TFs (POU3F2, SOX2, SALL2, OLIG2) has been identified that was sufficient to reprogram differentiated glioblastoma cells to CSCs." (PMID 33297508, 2020). "Four core transcription factors (POU3F2, SOX2, SALL2, and OLIG2) are reported to be essential for glioblastoma propagation and sufficient to fully reprogram differentiated glioblastoma cells into glioblastoma stem cells." (PMID 31375149, 2019). "A subset of only four of them–SOX2, OLIG2, POU3F2, and SALL2–was sufficient to fully reprogram differentiated cells into glioblastoma stem-like cells." (PMID 29773872, 2018). "Their expression in differentiated cells strongly correlated with the down-regulation of transcription factors like OLIG2, POU3F2, SALL2, SOX2, capable of reprogramming differentiated glioblastoma cells into stem-like cells." (PMID 29773872, 2018). "We found that ARNT2 knockdown not only impaired the cell tumorigenicity in vivo but also resulted in decreased expression of SOX9, POU3F2 and OLIG2, hence placing ARNT2 at the core of transcriptional regulations of glioblastoma cell tumorigenicity." (PMID 29149419, 2018). "POU3F2 and other neuro-developmental transcription factors (SOX2, SALL2 and OLIG2) coordinate to play essential roles in the progression of glioblastoma." (PMID 27271588, 2016). "For example, in glioblastoma, ARNT2 has been shown to be highly expressed in proliferative subpopulations and to promote tumorigenicity through the regulation of key transcription factors such as SOX9, POU3F2 (BRN2), and OLIG2." (PMID 40723431, 2025).